MUC1 (mucin 1, cell surface associated)
Diseases named in the same sentence as MUC1 in open-access papers (continued):
Sharing a sentence is not in itself a finding about the gene and the disease.
cancer (continued). "Using shRNA strategy and/or different MUC1 constructs, we found that MUC1-extracellular domain and MUC1-CT are involved in increase of migration, cell viability, resistance to anoikis and in decrease of cell aggregation in cancer cells." (PMID 24504508, 2014). "Mucin 1 (MUC1) is overexpressed in an incompletely glycosylated form in various human cancers." (PMID 24947606, 2014). "Galectin-3 interacts with MUC1 and regulates MUC1 expression and function in cancer cells." (PMID 25499743, 2014). "Accordingly, treatment of cancer cells with anti-MUC1 antibody inhibits EGFR signaling." (PMID 25499743, 2014). "Moreover, MUC1 promotes a metastatic phenotype of cancer cells by inducing EMT and activating the ZEB1/miR-200c regulatory loop." (PMID 25499743, 2014). "Indeed, Saores and colleagues have observed that MUC1 is more strongly expressed in carcinoma ex-PA by comparison to recurrent PA and PA." (PMID 24911657, 2014). "In the 108 cases, the positive expression rates (more than 5% of carcinoma cells stained) of each mucin antigen were MUC1, 47.2% (51/108); MUC2, 71.3% (77/108); MUC3, 18.5% (20/108); MUC4, 93.5% (101/108); MUC5AC, 50.0% (54/108); MUC6, 4.6% (5/108) MUC16, 16.7% (18/108) and MUC17, 86.1% (93/108)." (PMID 25551773, 2014). "As the invasive capacity of cancer cells depends in part on their ability to assemble invadopodia, the formation of the MUC1/CIN85 complex may be a requirement for this process." (PMID 24072600, 2013). "MUC1 associates with β-catenin, NF-κB and EGFR and translocates to the nucleus thereby regulating transcription of several genes responsible for progression and invasiveness of cancer." (PMID 24072600, 2013). "The majority of these are developing vaccination strategies against MUC1 to treat cancer." (PMID 23509794, 2013). "Therefore, MUC1 overexpression can attenuate many signals that induce an apoptotic response, leading to poor responsiveness to chemotherapy in cancer cells." (PMID 23708102, 2013). "Indeed, in cancer, soluble MUC1 presents an aberrant pattern of glycosylation, notably the Tn antigen, which can be recognized and internalized by the C-type lectin receptor macrophage galactose-type lectin (CLR MGL) present on DC and macrophages." (PMID 23509794, 2013). "In an earlier study, we reported that a cleaved form of the MUC1 transmembrane receptor, called MUC1*, that had previously only been detected on cancer cells is expressed on undifferentiated human embryonic stem cells and mediates their growth in an bFGF-independent manner." (PMID 23505541, 2013). "MUC1 decreases the adhesion between cancer cells and the adhesion between cancer cells and the extracellular matrix by altering the cytoskeleton, thus promoting the release of cancer cells from the primary lesion." (PMID 23708102, 2013). "Finally, to improve the MUC1 cDNA strategies, another interesting study suggested the use of a modified MUC1 sequence, in order to prevent normal glycosylation of the MUC1 protein in dendritic and cancer cells." (PMID 23509794, 2013). "Similarly, MUC1 was markedly overexpressed in cancer compared to normal tissue, especially in advanced stages of disease." (PMID 24072600, 2013). "This is consistent with previous studies showing that the tandem repeats of MUC1, and in particular the alterations in the length of the glycan chains, play a role in cancer progression, invasiveness and attachment of carcinoma cells to tissues at distant sites." (PMID 24072600, 2013). "The oncogenic function of MUC1 has been well reported in various cancers." (PMID 23405089, 2013). "It has also been shown that the MUC1 aptamers could be employed to selectively deliver phototherapy agent to cancer cells in vitro." (PMID 22384115, 2012). "The results again suggested that Apt-Dox could be selectively taken up by MUC1 positive cancer cells." (PMID 22384115, 2012).
cancer (continued). "However, intracellular expression of MUC1 extracellular domain antibody reactivity is found in cancer tissue and in normal uterine epithelial cells." (PMID 22905162, 2012). "It is therefore important to explore whether MUC1 aptamer can be used directly to selectively deliver cytotoxic agent to cancer cells." (PMID 22384115, 2012). "MUC1 is a 500–1000-kDa transmembrane glycoprotein expressed by normal and cancer cells." (PMID 23023583, 2012). "Downregulation of membrane-bound MUC1 discriminated cancer-free tissue from cancer tissue." (PMID 23028920, 2012). "When Dox is intercalated into the DNA structure of the MUC1 aptamer (Apt-Dox), the complex may preferentially bind to MUC1-positive cancer cells." (PMID 22384115, 2012). "During chronic inflammation, MUC1 expression is sustained at a high level, which may contribute to cancer development." (PMID 22457794, 2012). "Interestingly, another up-regulated gene in cancer cells grown with the CAFs, which contributes to cancer invasion is myelin-associated glycoprotein (MAG) that binds to the oncogenic glycoprotein MUC1." (PMID 22453032, 2012). "It is then reasonable to hypothesize that cancer’s adaptation and alteration of MUC1 may play a vital role in metastatic progression." (PMID 22866263, 2012). "The results indicated that the aptamer MA3 could preferentially bind to MUC1-positive cancer cells, and that the aptamer might recognize the MUC1 structure on these cells." (PMID 22384115, 2012). "We found that MA3 could specifically bind to MUC1-positive cancer cells, with minimal cross reactivity to albumin." (PMID 22384115, 2012). "The data again suggested that the Apt-Dox could selectively deliver drug to MUC1-positive cancer cells." (PMID 22384115, 2012). "Higher MUC1 expression in the membrane discriminated normal tissue from cancer (failure rate 2.1%)." (PMID 23028920, 2012). "MUC1 is a transmembrane mucin, whose over-expression is reported in most cancers." (PMID 22962849, 2012). "With the identification of cancer antigens in basic researches in recent years, several cancer-specific peptides, such as MUC-1, MART-1, TRP-2, gp100, NYESO, Her2/neu, and others, had been administered to cancer patients with an adjuvant, with or without dendritic cells." (PMID 22422103, 2012). "Furthermore, promoter-driven cancer gene therapy which exploits overactive MUC1 and MSLN promoters in various cancer types has been extensively studied in pre-clinical cancer models using viral vectors." (PMID 22792233, 2012). "One could envision isolating MUC1 glycopeptides directly from cancer cells, and analyzing them by mass spectrometry." (PMID 23023583, 2012). "The results suggest that MA3 may selectively recognize the MUC1 structure expressed on the surface of MUC1-expressing cancer cells." (PMID 22384115, 2012). "Taken together, our microscopy and flow cytometry data indicate that the aptamer MA3 may serve as a vehicle for targeted delivery of Dox to MUC1-positive cancer cells." (PMID 22384115, 2012). "Furthermore, MUC-1 expression correlates with cancer severity and is inversely correlated to patients’ survival prognosis." (PMID 22605971, 2012). "As such, antagonists of EGFR or integrin αvβ5 may provide new therapeutic options to target malignant tumors expressing MUC1." (PMID 22586492, 2012). "A library of monoclonal antibodies toward authentic MUC1 glycopeptide epitopes may be a valuable tool for studying glycan and peptide sequences in cancer, as well as reagents for diagnosis and therapy." (PMID 23023583, 2012). "MUC1 is not only overexpressed in many cancer types but is also aberrantly underglycosylated." (PMID 22866263, 2012). "However, like MUC1, there was a strong association between MSLN expression and early cancer-specific mortality (p<0.0001)." (PMID 22792233, 2012).
cancer (continued). "Due to the overexpression of MUC1 by almost all epithelial carcinomas, glycopeptide partial sequences with abnormal O-glycans contained in the MUC1’s tandem repeats are ideal potential antigens and biomarkers that could be detected by monoclonal antibodies." (PMID 23023583, 2012). "Humoral responses to MUC1 have also been observed in carcinoma patients." (PMID 24970145, 2012). "Among the carcinomas, we observed MUC1 activity in 68% of the analysed cases that displayed a strong immunostaining in a mixed pattern (involving the entire cell surface and the cytoplasm), which comprises the whole cell population in several carcinoma samples." (PMID 22726603, 2012). "The enhanced levels of MUC1 expression by cancer cells may mask extra-cellular domains from immune surveillance, conferring a survival advantage on malignant cells and playing an important role in the ability of tumors to invade and metastasize." (PMID 21931707, 2011). "However, only 10 different antigens are currently being targeted by mAbs developed for cancer therapies: EpCAM, MUC1, EGFR, CD20, CEA, HER2, CD22, CD33, Lewis Y and PSMA." (PMID 24212823, 2011). "Since many cancers overexpress MUC1 protein, we postulate that targeted drug delivery aiming at MUC1 may serve as a potential strategy to improve the treatment outcome of these tumors." (PMID 21912664, 2011). "In this work, an anti-MUC1 binder was isolated from an immune antibody phage display library constructed from MUC1 peptide vaccinated patients, a strategy which has been tested for different MUC1 positive cancers." (PMID 21264246, 2011). "Our data implicates non-cysteine linked MUC1 dimerization in cell signalling pathways required for cancer cell migration." (PMID 21798038, 2011). "In cancer patients, humoral and cellular responses against MUC1 have been detected." (PMID 22235224, 2011). "This would imply that targeting MUC1 signalling pathways by MAb C595 may reduce cancer proliferation, migration and invasion of metastatic EOC cells." (PMID 21931707, 2011). "Conceivably, C2-O-sLeX may be one of the oligosaccharides attached to MUC1 or another mucin present on cancer cells that may modulate their invasive properties." (PMID 21283832, 2011). "MUC1 consists of three domains (a large extracellular motif, a transmembrane motif, and a cytoplasmic tail) and mediates signal transduction events that stimulate the motility, invasion, and metastasis of cancer cells." (PMID 22235224, 2011). "The results suggest that the MUC1 aptamer may selectively enhance the delivery of anticancer drug to MUC1-positive cancer cells." (PMID 21912664, 2011). "We found that the mucins MUC1, MUC5AC, and MUC16 are indeed major cancer-associated carriers of CA 19-9, but because of the diversity among patients in the proteins that carry CA 19-9, the detection of CA 19-9 on any single protein did not out-perform total CA 19-9." (PMID 22220206, 2011). "MUC1 is shed into the circulation, and is elevated in the serum of carcinoma patients." (PMID 24212946, 2011). "A natural humoral immune response to MUC1 not only may have a favorable influence on disease outcome in patients with carcinoma, but may also protect against the development of the disease." (PMID 24212946, 2011). "Adjuvant vaccination with MUC1 glycopeptide polyvalent vaccines that induce strong humoral responses may prevent recurrence of disease in patients with early stage carcinomas." (PMID 24212946, 2011). "NK cells were the principal effector cells for MUC1 ab-dependent killing, which could be inhibited by serum samples of carcinoma patients with high levels of MUC1." (PMID 24212946, 2011).
cancer (continued). "We found early on that natural humoral responses to MUC1 peptides go hand in hand with humoral responses to MUC1 glycopeptides, and that sera from carcinoma patients react more strongly with triple TR TnMUC1 (GalNAc-MUC1) glycopeptides than with the corresponding naked peptides." (PMID 24212946, 2011). "According to this hypothesis, this would then render MUC-1 specific antibodies a part of an effective immune response against cancer cells." (PMID 21234352, 2010). "Independent of the expression system used, the bi- or tribody molecules bound to their MUC1 targets with equal effectiveness either in a peptide context or on OVCAR3 cancer cells, indicating the mammalian and yeast expression products were of similar specific activity." (PMID 19671134, 2009). "It is striking to note that MAL2, a chromosome 8q24 amplification target, has now been shown to bind MUC1 and D52, both of which are amplified and/or overexpressed in breast and other cancers strongly suggesting that these proteins have co-operating functions in cancer cells." (PMID 19175940, 2009). "This construct may allow multimodal therapy, combining virotherapy with radioiodine therapy to be developed as a novel treatment for breast and other MUC1-overexpressing cancers." (PMID 19635153, 2009). "Thus, high expression of MUC1, as occurs in the stomach and is commonly found in human cancers, confers increased proliferation and resistance to apoptosis both via ß-catenin and the NF-κB pathway." (PMID 19816567, 2009). "Moreover, the cytoplasmic tail of mucins like MUC1 is known to induce several cell signaling pathways, which promote the cell growth and proliferation in a variety of cancer cells." (PMID 20034397, 2009). "Indeed, recent studies showed that MUC1 overexpression in carcinoma cells increases their refractoriness to chemotherapeutic drug-induced apoptosis." (PMID 19672266, 2009). "For many years researchers had observed a link between the aberrant expression of MUC1 and cancer." (PMID 18446242, 2008). "Importantly, direct binding between NM23 and MUC1* peptides was detected for the same concentration range at which NM23 stimulated cancer cell growth." (PMID 18446242, 2008). "We next tested the ability of exogenous NM23 to stimulate the growth of MUC1-positive cancer cells." (PMID 18446242, 2008). "It has been shown that the cytoplasmic tail of MUC1 may affect actin polymerisation and increase motility in cancer cells." (PMID 18665193, 2008). "NM23 is normally found in the cytoplasm of all cells but is often secreted by cancer cells indicating that it could be a ligand for the extracellular portion of MUC1*." (PMID 18446242, 2008). "If MUC1 or MUC1* functions as a growth factor receptor that is activated by dimerization of the extracellular domain, then it follows that MUC1-positive cancer cells may secrete a dimerizing ligand(s)." (PMID 18446242, 2008). "Alternatively, these results might simply be explained by the fact that the major species on cancer cells is the cleaved form, MUC1*." (PMID 18446242, 2008). "Mouse studies have been integral to the current understanding of MUC1 in cancer." (PMID 16846534, 2006). "To date, clinical trials against MUC1 have included advanced cancer patients." (PMID 16776849, 2006). "The overexpression of MUC1 mucin plays an important role in cancer metastasis." (PMID 15599383, 2004). "Overexpression of MUC1 in cancer cells may effect efficient lysis by cytotoxic lymphocytes and therefore contribute to escape from immune surveillance." (PMID 15599383, 2004). "Moreover, the glycosylation patterns of MUC1 in cancer cells are frequently abnormal." (PMID 40333213, 2025). "Due to the strong evidence regarding the correlation between MUC1 and drug resistance in malignant tumors, MUC1 became the promising target of new therapeutic strategies based on the inhibition of its expression or functions, which could improve PDAC patient responses to conventional therapies." (PMID 40001578, 2025).
cancer (continued). "Furthermore, the interaction between MUC1 and EGFR may partially promote drug resistance by activating the IL-6 signaling pathway, which is implicated in cancer stem cell enrichment and subsequent chemotherapy failure." (PMID 40655139, 2025). "Overall, these FEL profiles validate the ternary complex’s improved energetic and structural stability, reinforcing the hypothesis that dual-targeting of MUC1 by PTX and HNK promotes structural consolidation and could offer enhanced therapeutic efficacy in MUC1-driven cancers." (PMID 41471303, 2025). "Therefore, the regulation of NEAT1 and paraspeckles formation indicates a novel mechanism by which MUC1-CT may influence cancer biology, suggesting the potentiality of targeting these signaling pathway for future treatments in PDAC." (PMID 40001578, 2025). "Thus, Tn‐MUC1 has the potential to be a new therapeutic application for other cancers." (PMID 40844495, 2025). "Therefore, MUC1 has been one of the major targets for cancer vaccine development." (PMID 41012179, 2025). "Based on our findings, there was no indication that MUC1 caused VTE in cancer patients." (PMID 39061213, 2024). "As cancer vaccines, mRNA encoding cytokines, such as Interleukin-12 (IL-12), IL-27, IL-23, IL-36γ, and INF-α; antigens, such as OX40L, OVA, cytokeratin 19 (CK19), and MUC1; or antibodies that block immune checkpoints, such as anti-PD-1 and anti-PD-L1, can be used." (PMID 39407665, 2024). "Consequently, MUC1 has been also employed as a target for cancer vaccine strategies." (PMID 39737308, 2024). "Moreover, analysis of patients with grade 3 TNBCs treated with cytotoxic anti-cancer agents demonstrated that those with MUC1-high and NEAT1-high tumors had significantly decreased relapse-free survival, supporting involvement of the MUC1-C/NEAT1 pathway in conferring chemoresistance." (PMID 38802648, 2024). "Therefore, MUC1 overexpression can enhance cancer cell proliferation by modulating cell metabolism." (PMID 38540735, 2024). "One of the more interesting TAAs for targeting TNBC is Mucin 1 (MUC1), a hyperglycosylated, immunologically unavailable protein in many normal epithelial cells but a hypoglycosylated, immunologically available protein in several malignant tumors, including TNBC67." (PMID 36781869, 2023). "Given this immune response, a C3-liposome-based vaccine formulation could possibly be used prophylactically as a vaccine to prevent the development of cancers with aberrant MUC1 expression, as well as in cancer treatment settings to enhance the immune recognition of MUC1-expressing cancer cells." (PMID 38140114, 2023). "MUC1 has been associated with the progression of GBC, and Skp2 may be an independent prognostic factor for GBC; these studies suggested the potential roles of these factors in the occurrence and development of cancer." (PMID 36624399, 2023). "As MUC1 forms the mucosal surfaces of many tissues representing a protective layer against external insults and it is aberrantly expressed in cancer, we monitored whether TG2-mediated transamidation could alter MUC1 post-translationally as well as concur to its production." (PMID 37160910, 2023). "Thus, T cell-engaging MUC1/CD3 BsAb could be an effective therapeutic approach to combat MUC1-positive tumors and our MUC1/CD3 BsAb could be a promising candidate in clinical applications for the treatment of MUC1-positive cancer patients." (PMID 37489369, 2023). "Therefore, there is great potential for labeling antibodies or aptamers to MUC1 with radionuclides, which could enhance the therapeutic effect of drugs for cancer treatment." (PMID 37894512, 2023). "In addition to elevated expression, MUC1 on cancer cells undergoes aberrant glycosylation." (PMID 37894512, 2023).